MMRN1 (multimerin 1)
Diseases named in the same sentence as MMRN1 in open-access papers (continued):
Sharing a sentence is not in itself a finding about the gene and the disease.
cancer (29 papers, 2013 to 2025). A tumor composed of atypical neoplastic, often pleomorphic cells that invade other tissues. "Although the gene has been mostly studied in the context of cancer metastasis, a transcriptome-wide association analysis recently identified MMRN1 as a gene whose expression associates with PD risk." (PMID 38323005, 2024). "Below, we are discussing examples of potential regulatory mechanisms, including methylation, ncRNAs and transcription factors, which have been associated with MMRN1 expression levels in cancers." (PMID 35132992, 2022). "Cancer plasticity is associated with changes in gene expression patterns, which is why MMRN1’s differential expression pattern in cancer is of great interest." (PMID 35132992, 2022). "The observed correlation between MMRN1 expression and cancer risk scores highlights MMRN1 relevance in the disease process." (PMID 35132992, 2022). "MMRN1, a platelet protein known for its role in blood clotting, had been understudied in the context of cancer according to the literature." (PMID 40583724, 2025). "The interaction between MMRN1 and platelets facilitates the evasion of natural killer cells by circulating cancer cells, enabling their adhesion to blood vessel walls." (PMID 40583724, 2025). "Recent research has identified MMRN1 as a differentially expressed gene (DEG) in various cancers, suggesting its potential as a cancer biomarker." (PMID 40583724, 2025). "As a gene connected with poor prognosis, MMRN1 is regulated by methylation, protein interactions, and non-coding RNAs (ncRNAs) across various cancers." (PMID 41296429, 2025). "In regard to GC, MMRN1 can interact with platelets to promotes the evasion of circulating cancer cells from natural killer cells, recruit ECM and granulocytes, and release angiogenic growth factors, thereby leading to the occurrence and metastasis of GC68." (PMID 40032943, 2025). "Recent research has highlighted MMRN1 as a differentially expressed gene (DEG) in various cancers, suggesting its potential utility as a cancer biomarker." (PMID 40583724, 2025). "Whereas the role of other EMILIN/multimerin family members in cancer has been the focus of various studies, a molecular mechanism for MMRN1 is yet to be described." (PMID 35132992, 2022). "Considering the cancer-specific differential expression patterns of MMRN1 and possible application in cancer diagnosis, details on the regulatory mechanisms driving these expression patterns is relatively scarce." (PMID 35132992, 2022). "In gastrointestinal stromal tumours, MMRN1 was identified as the host gene of the circRNA hsa_circ_0070442 and both are downregulated in this cancer." (PMID 35132992, 2022). "Most information on possible transcription factors that target MMRN1 in various cancers is currently available through bioinformatics analyses and offer an interesting starting point for future in vitro and in vivo experiments." (PMID 35132992, 2022). "Some evidence suggest that MMRN1 expression is regulated by methylation, protein interactions, and non-coding RNAs (ncRNAs) in different cancers." (PMID 35132992, 2022). "SWATH-MS identified a positive correlation between MMRN1 and thrombospondin 1 expression, which is differentially regulated in cancers, in the blood plasma of five cancers (colorectal, pancreatic, lung, prostate, ovarian)." (PMID 35132992, 2022). "This raises the questions if a functional role of MMRN1 is being targeted during cancer development, and if MMRN1’s differential expression pattern correlates with cancer progression." (PMID 35132992, 2022). "MMRN1’s potential as a biomarker in certain cancers, including diagnosis of cancer stages, is a strong possibility." (PMID 35132992, 2022). "As a result, it is timely to review the current state of what is known about MMRN1 to help inform future research into MMRN1’s molecular mechanisms in cancer." (PMID 35132992, 2022). "Can MMRN1 expression levels help diagnose cancer and/or cancer stages?" (PMID 35132992, 2022).
cancer (continued). "Stromal cells (or cancer-associated cells) included endothelial cells (PECAM1/CD31+ and MMRN1+), fibroblasts (COL6A1+, COL1A1+, THY1+, and DCN+), epithelial cells (LAMC2+, KRT5+, and KRT14+), and unassigned name cells (high heat shock proteins expression), suggesting that they were cancerous cells." (PMID 35742914, 2022). "Exosomes are able to promote metastasis, but how MMRN1 exosomal release is associated with cancer progression has not been investigated yet." (PMID 35132992, 2022). "Considering the importance of integrins in cancer, analysis of MMRN1–intergrin interactions in the context of ECs and ECM in cancer may reveal new MMRN1 interaction partners and functions." (PMID 35132992, 2022). "MMRN1 is expressed in various cancer cell lines, and a DEG in various cancers." (PMID 35132992, 2022). "Further refinement of this matrix risk signature to specifically predict which lesions will progress to cancer identified a minimum 6-gene risk signature of RSPO1, CTHRC1, SPP1, MMRN1, COL10A1, and PRG4 as the most significant matrisomal predictors of premalignant progression with a ROC AUC of 0.99." (PMID 36404344, 2022). "The oncogenic role of MMRN1 is clear in several human cancers." (PMID 32175193, 2020). "Therefore, biochemical and structural studies into MMRN1’s mechanistic roles are needed and may provide support for MMRN1’s use in cancer diagnosis and prognosis." (PMID 35132992, 2022). "It is also unclear if MMRN1’s functions are indiscriminatory of its cellular locations, platelets, ECs and the ECM, which all play roles in cancer." (PMID 35132992, 2022). "In recent years, MMRN1 has been identified as a differentially expressed gene (DEG) in various cancers and it has been proposed as a possible cancer biomarker." (PMID 35132992, 2022). "In this study, other genes coding for proteins with a role in cell adhesion were identified, but of the original 206 genes, only 18 gene candidates (not including MMRN1) were considered as relevant to cancer development." (PMID 35132992, 2022). "No functional relation to cancer biology is known, but MMRN1 was identified as negative prognostic marker in pediatric AML." (PMID 31717802, 2019). "The in vitro data on MMRN1 peptides corresponding to EGF, gC1q and coiled-coil regions in promoting cell proliferation, as well as MMRN1’s potential role in cell adhesion and cell–cell communication, certainly warrant further investigations into MMRN1 physiological roles in cancer." (PMID 35132992, 2022).
tumor (25 papers, 2007 to 2025). "The combined analysis revealed sex, race, TMB, neoplasm histologic grade, Child–Pugh grade, MMRN1, OXT and COX6A2 transcription as independent risk factors." (PMID 36153509, 2022). "Future studies must include animal models to confirm the functional significance of MMRN1 in tumor growth and metastasis." (PMID 41296429, 2025). "Sex, race, TMB, neoplasm histologic grade, Child–Pugh grade, MMRN1, OXT and COX6A2 transcription have been identified as independent risk factors." (PMID 36153509, 2022). "The results showed that 5 proteins (ADAM23, ARHGAP20, ICOS, IRF4,MMRN1) were significantly different in tumour tissues compared with normal tissues." (PMID 33949771, 2021). "The tumor growth curves between control and MMRN1‐OE groups were compared and analyzed." (PMID 40583724, 2025). "Does MMRN1 interact with tumour cells via protein–protein interactions?" (PMID 35132992, 2022). "Finally, 19 prognostic genes were verified by GSE17536 and GSE17537 from GEO, and five genes (ADAM23, ARHGAP20, ICOS, IRF4,MMRN1) were significantly different in tumour tissues compared with normal tissues at the protein level." (PMID 33949771, 2021). "Drawing from current literature, we propose that MMRN1 functions as an oncogene in RCC, facilitating tumor proliferation and metastasis through the AMPK pathway." (PMID 40583724, 2025). "Compared with tumor cells at the primary site, metastatic tumor cells still retained high expressions of KRT8 and KRT18, whereas metastatic tumor cells no longer expressed MMRN1, PROX1, TCF7L1, SCG3 and SV2C." (PMID 35494058, 2022).
MMRN1 also shares sentences with these, for which no sentence is quoted: non-small cell lung carcinoma (3 papers); colorectal adenocarcinoma (2); COVID-19 (2); lung fibrosis (2); Marfan syndrome (2); osteogenesis imperfecta (2); progeria (2); thyroid cancer (2); autonomic dysfunction (1); cardiac hypertrophy (1); cardiomyopathy (1); cleft palate (1); cognitive decline (1); colon cancer (1); colorectal tumor (1); coronary artery aneurysms (1); depression (1); duodenal cancer (1); duodenum adenocarcinoma (1); esophageal cancer (1); fibrosis (1); glaucoma (1); gout (1); gray platelet syndrome (1); Hepatic steatosis (1); hepatocellular carcinoma (1); hypothyroidism (1); infection (1); keloid (1); keratoconus (1).
A further 22 diseases each share a sentence with MMRN1 in 1 paper.